MTOR (mechanistic target of rapamycin kinase)
Diseases named in the same sentence as MTOR in open-access papers (continued):
Sharing a sentence is not in itself a finding about the gene and the disease.
gastric cancer (continued). "These confirmed results influence with our previous study that the down-regulation PI3K/Akt/mTOR pathway leads to G2/M phase cell cycle arrest, autophagic, and apoptotic cell death in gastric cancer treated with PEC." (PMID 30380781, 2018). "LMO3 has been proved to promote cell invasion or proliferation through Akt-mTOR/GSK3β signaling in gastric cancer." (PMID 30219064, 2018). "The PI3K/AKT/mTOR pathway is frequently hyperactivated in many cancers, including gastric cancer, and is important for aggressive tumor growth and cell survival." (PMID 30096805, 2018). "Although studies investigating lactobacilli effects on cell turnover are very scarce, another lactobacilli species has been reported to induced apoptosis in gastric cancer cells by inhibiting NF-κB and mTOR-mediated signaling." (PMID 30013538, 2018). "In conclusion, we found that miR-361-5p suppressed autophagy-induced chemoresistance of gastric cancer cells through targeting FOXM1 via the PI3K/Akt/mTOR pathway, providing a foundation for the mechanism research and treatment of gastric cancer." (PMID 29435149, 2018). "In our previous study, PEC treatment showed an anti-cancer effect by inducing G2/M phase cell cycle arrest, autophagic, and apoptotic cell death in human gastric cancer cells by the down-regulation of PI3K/AKT/mTOR pathway." (PMID 30380781, 2018). "PI3K/AKT/mTOR signaling is one of the comprehensive pathways activated in most cancers, including gastric cancer." (PMID 30096805, 2018). "That is to say, inhibit Gli1 both via HER2–Akt–mTOR–p-70S6K and Hedgehog pathway has synergistic effect on gastric cancer cells." (PMID 29321573, 2018). "As revealed by western blot analysis, the expression of DDX5 and p-mTOR demonstrated a strong correlation in gastric cancer tissues." (PMID 28216662, 2017). "In conclusion, our study demonstrates that DDX5 promote gastric cancer cell proliferation via mTOR signaling." (PMID 28216662, 2017). "The molecular mechanism of UCA1 suggested that UCA1 regulates the PI3K-Akt-mTOR signaling proteins and their downstream mediators, to alter gastric cancer progression in vitro and in vivo." (PMID 29212166, 2017). "More accurate studies are thus required to better understand if PI3K/AKT/mTOR are indeed “drivers” in some gastric cancer and to define the most efficient drugs." (PMID 28915702, 2017). "While cancer cells of the metabolic subtype were measured more sensitive to 5-FU, gastric cancer cells of the mesenchymal subtype responded to a greater degree to PI3K/mTOR inhibition." (PMID 28460635, 2017). "Intriguingly, we also observed a positive correlation between DDX5 and p-mTOR in gastric cancer tissues." (PMID 28216662, 2017). "A study on CDX2 heterozygous knockout mice demonstrated CDX2 haploinsufficiency led to an increase in mTOR kinase activity and CDX2 overexpression in gastric cancer cells induced an increase of mTOR mRNA and protein expression." (PMID 29156556, 2017). "The study of the molecular mechanism of UCA1 suggested that UCA1 regulates PI3K-Akt-mTOR signaling proteins and their downstream mediators, and alters gastric cancer progression in vitro and in vivo." (PMID 29212166, 2017). "Taken together, these results revealed a novel role of DDX5 in gastric cancer cell proliferation via the mTOR pathway." (PMID 28216662, 2017). "For example, there is an increasing interest in studying the role of the mammalian target of rapamycin (mTOR) in gastric cancer." (PMID 28446188, 2017). "The effects of the mTOR rs2295080 GT/GG genotypes were also observed in esophageal squamous cell carcinoma, gastric carcinoma, and renal cell carcinoma." (PMID 28977864, 2017). "Beside the direct toxic effects, PPIs were also able to inhibit mTOR signaling and other metabolic pathways in gastric carcinoma cell line, and to potentiate the antitumor effectiveness of Adriamycin in mice harboring gastric carcinoma xenografts." (PMID 29295495, 2017).
gastric cancer (continued). "The expression of phosphorylated mTOR is a prognostic factor for gastric cancer that negatively correlates with cancer prognosis." (PMID 26728266, 2016). "Treatment with rapamycin to block mTOR impairs growth of GLI2A-driven gastric cancers while triggering aberrant induction of mucous production by tumor cells." (PMID 26859571, 2016). "H19 and its mature product miR-675 enhanced the proliferation and invasion of gastric cancer AGS cells by activation of Akt/mTOR pathway, in which tumor suppressor RUNX1 served as a pivotal mediator." (PMID 27738631, 2016). "Among these inhibitor, PP242 is a dual mTORC1 and mTORC2 inhibitor that similar with DEPTOR, which has been reported to suppress proliferation, metastasis, and angiogenesis of gastric cancer cells through inhibition of the PI3K/AKT/mTOR pathway." (PMID 26893358, 2016). "Association between the clinicopathological parameters and mTOR, p-mTOR expression in 120 cases of gastric cancer." (PMID 28005970, 2016). "It has been reported that the mammalian target of the rapamycin (mTOR) signaling pathway is frequently activated in gastric cancer cells." (PMID 26880889, 2016). "Preclinical research showed that, in in vitro studies and in animal models, blockage of the mTOR signaling pathway can inhibit the proliferation and metastasis of gastric cancer cells." (PMID 26880889, 2016). "Inhibition of these receptor tyrosine kinases consequently attenuated the activation of the downstream AKT/mTOR signaling pathway both in cultured gastric cancer cells and in gastric cancer xenografts." (PMID 27387652, 2016). "At present, several factors, such as HER2, VEGF, FEGFR, and mammalian target of rapamycin (mTOR), have been considered as targets of therapy for gastric cancer." (PMID 27403158, 2016). "The mTOR inhibitor everolimus inhibits the mTOR/S6K signal, and therefore improves fluorouracil-induced apoptosis in gastric cancer cells with HER2 amplification." (PMID 27795701, 2016). "We conclude that ADAR1 contributes to gastric cancer development and progression via activating mTOR/p70S6K/S6 ribosomal protein signaling axis." (PMID 27863387, 2016). "The interaction of MTOR rs1064261 and AKT rs1130233 polymorphisms in the risk of atrophic gastritis and gastric cancer*." (PMID 26317520, 2015). "Different dosages of p-Akt inhibitor LY294002 (12.5 μM, 25 μM, 50 μM) and p-mTOR inhibitor Rapamycin (25 nM, 50 nM, 100 nM) were given to gastric cancer cell line SGC-7901 in vitro." (PMID 25884175, 2015). "Increasing evidences suggested that mTOR can be activated by Akt signaling pathway in gastric cancer." (PMID 26500453, 2015). "Correlation between MTOR rs1064261 or AKT rs1130233 polymorphisms and clinicopathological parameters in gastric cancer." (PMID 26317520, 2015). "Everolimus, an oral mTOR inhibitor, was investigated in advanced gastric cancer in the GRANITE-1 study." (PMID 25784931, 2015). "The mTOR inhibitor has been confirmed to induce cell cycle arrest and apoptosis of gastric cancer cell line." (PMID 26500453, 2015). "The level of LVD in gastric cancer specimens was significant higher than that of normal gastric tissue and was positively correlated with p-Akt, p-mTOR, VEGF-C and VEGF-D." (PMID 25884175, 2015). "miR-21 mimic was used to up-regulate miR-21 expression and mTOR expression plasmid was used to increase mTOR level in gastric cancer cells." (PMID 26500453, 2015). "In gastric cancer cells treated with celastrol for 16 h, p27 was significantly reduced, while activation of mTOR rescued this protein level dramatically." (PMID 26500453, 2015). "Association of mTOR rs1064261 and AKT rs1130233 polymorphisms with the risk of atrophic gastritis and gastric cancer." (PMID 26317520, 2015). "There is no report yet focusing on the modulation of VEGF pathway and lymphangiogenesis of gastric cancer by targeting Akt/mTOR pathway." (PMID 25884175, 2015).
gastric cancer (continued). "Available clinical trial data show that the mTOR inhibitor is effective to treat gastric cancer patients in combination with chemotherapeutic agents." (PMID 26500453, 2015). "Activated mTOR has been positively correlated with tumor progression and poor survival in patients with gastric cancer." (PMID 26500453, 2015). "The level of LVD in gastric cancer specimens was significant higher than that of normal gastric tissue and positively correlated with immunohistochemistry staining of p-Akt, p-mTOR, VEGF-C and VEGF-D." (PMID 25884175, 2015). "In a parallel proof-of-principle approach, we treated MKN45 gastric cancer cells with rapamycin to investigate the effect of mTOR inhibition on MMP expression." (PMID 26652716, 2015). "By treatment of MKN45 gastric cancer cells with rapamycin, a reduction of p-mTOR in the Western blot was achieved; however, expression of MMPs remained unaffected." (PMID 26652716, 2015). "In this study, the positive staining rates of p-Akt and p-mTOR in 55 cases of gastric cancer were 74.54% and 85.45% respectively." (PMID 25884175, 2015). "For intestinal type gastric cancer there was a weak correlation of MMP9 with expression of mTOR in the tumor center." (PMID 26652716, 2015). "Immunohistochemistry for leptin signalling-related proteins (leptin, leptin-receptor, pSTAT3, ERK, pAkt, mTOR and HIF-1 alpha), and in situ hybridization for EBV-encoded small RNAs was performed in 343 cases of gastric carcinomas." (PMID 26147886, 2015). "Leptin signaling-related proteins were commonly expressed in gastric carcinomas except for pSTAT3; pAkt positive in 79% (271/343) of gastric carcinomas, mTOR in 49% (169/33), HIF-1 alpha in 36% (123/343), ERK in 29% (101/343), and pSTAT3 in 8% (29/343)." (PMID 26147886, 2015). "Correlation between clinicopathological features and the GOPLH3, p-mTOR expression in gastric cancer specimen." (PMID 25286393, 2014). "In this study, we investigated clinical significances of GOLPH3 and AKT/mTOR signaling in gastric cancer." (PMID 25286393, 2014). "Inhibition of oncogenic signaling i.e. Akt/mTOR with targeted small molecule inhibitors is a powerful therapeutic approach to treat gastric cancer and possibly other solid tumors." (PMID 24416349, 2014). "Meanwhile, we discovered the relation of GOPLPH3 and Akt/mTOR signaling in gastric cancer to reveal the potential role of GOLPH3 in regulating mTOR-mediated gastric cancer tumorigenesis, invasion and metastasis." (PMID 25286393, 2014). "Western blotting analysis showed that GOLPH3, p-mTOR, p-Akt1, p-4EB-P1 and p-p70S6 were also expressed in the gastric cancer, carcinoma-adjacent, and paired normal gastric mucosa groups." (PMID 25286393, 2014). "The GOPLH3 expression level is highly correlated with Akt/mTOR signaling in human gastric cancer samples." (PMID 25286393, 2014). "PI3K/mTOR pathway activation has been demonstrated in gastric cancer and everolimus (Afinitor) has shown some significant response in the gastric cancer patients through targeting the mutations associated with PI3K/mTOR pathway." (PMID 25025766, 2014). "GOLPH3 and phosphorylated Akt/mTOR pathway proteins were more highly expressed in the gastric cancer group than in the para-carcinoma tissue and paired normal mucosa groups." (PMID 25286393, 2014). "Compared with carcinoma-adjacent and paired normal tissues, the mRNA expression levels of GOLPH3, AKT, mTOR, p70S6 and 4EBP1 in gastric cancer tissues were significantly higher." (PMID 25286393, 2014). "In this study, 81.25% of the 80 patients with gastric cancer had high p-mTOR expression, 77.50% had high p-4E-BP expression, 76.25% had high p-p70S6 expression, and only 75.00% had high p-Akt expression." (PMID 25286393, 2014). "Most of the genetic mutations in gastric carcinoma correlate with changes in biological signals, such as those in the phosphatidylinositol 3-kinase/Akt/mammalian target of rapamycin pathway (PI3K/Akt/mTOR pathway)." (PMID 25003395, 2014).
gastric cancer (continued). "Several factors mediate the metastatic capacity of gastric carcinoma through the PI3K/Akt/mTOR pathway." (PMID 25003395, 2014). "Genetic alterations in the PI3K/Akt/mTOR pathway in gastric carcinoma have been demonstrated frequently." (PMID 25003395, 2014). "The PI3K and mTOR inhibitor, PI103, acted in synergy with 5-FU in PIK3CA-mutated gastric carcinoma cells." (PMID 25003395, 2014). "Several other factors, including transcription factors, have been confirmed as mediators of chemoresistance through the PI3K/Akt/mTOR pathway in gastric carcinomas." (PMID 25003395, 2014). "Improved knowledge of the PI3K/Akt/mTOR pathway in gastric carcinoma will be useful in understanding the mechanisms of tumor development and for identifying ideal targets of anticancer therapy for gastric carcinoma." (PMID 25003395, 2014). "An immunohistochemical study showed positive correlations between mTOR expression in gastric carcinomas and pathological parameters such as invasive depth, differentiation, and lymph node metastasis." (PMID 25003395, 2014). "This review summarizes the current knowledge on PI3K/Akt/mTOR signaling in the pathogenesis of gastric carcinoma and the possible therapeutic targets for gastric carcinoma." (PMID 25003395, 2014). "Although there is substantial evidence that the PI3K/Akt/mTOR pathway is frequently altered in gastric carcinoma, its precise function remains to be determined." (PMID 25003395, 2014). "Patient-derived gastric cancer samples have been shown to express phosphorylated mTOR indicative of mTOR activation, which has been positively correlated with tumor progression and poor survival in patients with gastric cancer." (PMID 23930209, 2013). "Taxanes have shown therapeutic effects against gastric cancer while also activating the PI3K/mTOR signaling pathway." (PMID 24042258, 2013). "Several preclinical studies have indicated dysregulation of mTOR activity in gastric cancer cell models." (PMID 23930209, 2013). "They showed that the mammalian target of rapamycin (mTOR) is highly activated in gastric cancer specimens." (PMID 24216696, 2013). "Stratified analyses of mTOR rs2295080 genotype frequencies in gastric cancer patients and healthy controls by age and sex." (PMID 23555892, 2013). "Sixty-three gastric cancer tissues with different genotypes of mTOR rs2295080 were available in our present study." (PMID 23555892, 2013). "mTOR inhibitors alone or in combination with other agents significantly delayed tumor progression in xenograft models of gastric cancer." (PMID 23930209, 2013). "We investigated the effects of NVP-BEZ235 (BEZ235), a novel dual PI3K/mTOR inhibitor, alone and in combination with nanoparticle albumin-bound (nab)-paclitaxel in experimental gastric cancer." (PMID 24042258, 2013). "BEZ235, alone or in combination, blocked PI3K/mTOR pathway proteins in these three gastric cancer cell lines in vitro and in SNU16 xenograft tumor tissues." (PMID 24042258, 2013). "As an imperative part of PI3K/Akt/mTOR pathway, mammalian target of rapamycin (mTOR) has been demonstrated to increase in gastric cancer cells and tumors." (PMID 23555892, 2013). "NVP-BKM120 demonstrated anti-proliferative activity in 11 human gastric cancer cell lines by decreasing mTOR downstream signaling." (PMID 22159814, 2012). "The expression of p-mTOR was detected in specimens of 181 gastric cancers who underwent radical resection (R0) by immunohistochemistry." (PMID 20929525, 2010). "Our findings indicated that p-mTOR would serve as a potential biological marker to identify a subgroup of gastric cancer patients of poor prognosis." (PMID 20929525, 2010). "Further studies are required to elucidate the role of the activation of mTOR and eventually to propose mTOR as a concrete target for gastric cancer therapy." (PMID 20929525, 2010). "In the current study, we observed that 93 (51.4%) patients had positive expression of p-mTOR in 181 gastric cancer patients." (PMID 20929525, 2010).
gastric cancer (continued). "Immunostaining for p-mTOR was positive in 93 of 181 (51.4%) gastric cancers, closely correlated with lymph node status and pTNM stage." (PMID 20929525, 2010). "Their results highlight the suitability of mTOR inhibitors to be used in an antiangiogenic context for therapy of gastric cancer." (PMID 20929525, 2010). "In summary, we conducted systematical research to mTOR in gastric cancer, indicating the relationships the expression with the prognosis value of activated mTOR (p-mTOR) in vivo, the effect of RAD001 and the part of mechanisms in gastric cancer cells in vitro." (PMID 20929525, 2010). "Cytoplasmic p-mTOR expression correlates with poorer survival in gastric cancer and cervix adenocarcinoma." (PMID 20338061, 2010). "Consistent with our current study, several studies have also recognized the antiproliferative effects of mTOR inhibitors in gastric cancer cells." (PMID 20929525, 2010). "The correlation of p-mTOR expression to clinicopathologic features and survival of gastric cancer was studied." (PMID 20929525, 2010). "This study examined correlations of phosphorylated mTOR (p-mTOR) expression with clinicopathological features, outcomes, and p-Akt expression in gastric cancer." (PMID 19223902, 2009). "Our study showed that p-mTOR expression was significantly related to tumour progression and outcomes in patients with gastric cancer." (PMID 19223902, 2009). "We evaluated the correlation of mTOR expression with clinicopathological features, outcomes, and the expression of Akt, an upstream regulator of mTOR, in gastric cancer." (PMID 19223902, 2009). "Multivariate analysis showed that age, depth of invasion, lymphatic invasion, lymph node metastasis, Lauren's classification and mTOR expression were independent prognostic factors for overall gastric carcinomas (p < 0.05)." (PMID 20003385, 2009). "Multivariate analysis demonstrated six independent prognostic factors such as age, depth of invasion, lymphatic invasion, lymph node metastasis, Lauren's classification and mTOR expression were independent prognostic factors for overall gastric carcinomas." (PMID 20003385, 2009). "To investigate the role of mTOR signal pathway in the stepwise development of gastric carcinomas, we analyzed the correlations between the mTOR and P70S6K expression and clinic pathological factors and studied its prognostic role in gastric carcinomas." (PMID 20003385, 2009). "Nuclear p-p70S6K was a good marker to indicate the favorable prognosis of gastric carcinoma patients, albeit dependent on other parameters, but mTOR expression was an independent factor for the prognosis." (PMID 20003385, 2009). "Therefore, miR-21 and Helicobacter pylori together activate the PI3K/AKT/mTOR pathway, with possible synergistic effects in promoting gastric cancer cells proliferation, inhibiting autophagy and inducing DDP resistance." (PMID 40296912, 2025). "Furthermore, Hes1 collaborates with the Wnt/β-catenin, Hedgehog, and mTOR pathways to promote gastric cancer progression, indicating potential for combination therapy." (PMID 40755759, 2025). "THBS3 activated PI3K/AKT/mTOR signaling through protein kinase B (PKB) in gastric cancer." (PMID 40941410, 2025). "In addition, BP increases REDD1 expression in gastric cancer cells, inhibiting the mTOR signal pathway." (PMID 41049453, 2025). "Furthermore, it was demonstrated that CSNK2A1 regulates epithelial-to-mesenchymal transition (EMT) and enhances the invasiveness of gastric cancer cells through the PI3K–Akt–mTOR signaling pathway." (PMID 40453647, 2025).